LINC02551 (long independently transcribed non-coding RNA 2551)
Synonyms: JunBP; RP11-890B15.2
Gene: Long non-coding RNA gene on chromosome 11 (130,807,889 to 130,865,561, reverse strand). Ensembl gene ENSG00000254842.
Diseases named in the same sentence as LINC02551 in open-access papers:
LINC02551 is named in the same sentence as 3 diseases in open-access papers, as found by Europe PMC text mining. Sharing a sentence is not in itself a finding about the gene and the disease. The quoted sentences say what the papers report.
hepatocellular carcinoma (2 papers, 2023 to 2024). A malignant tumor that arises from hepatocytes. "JunBP, a micropeptide encoded by LINC02551, which is upregulated in HCC cells upon TGF-β stimulation, supports hepatocellular carcinoma metastasis by binding to c-Jun to promote its phosphorylation activation." (PMID 38622617, 2024).
breast carcinoma (1 paper, 2022). "However, this axis explained only the prometastatic roles of LINC02551, and whether the mechanism of the LINC02551 proliferation effect in HCC is in line with that in breast cancer is unclear and remains to be further studied." (PMID 36335087, 2022).
LINC02551 also shares sentences with these, for which no sentence is quoted: tumor (2 papers).